RNU6-859P (RNA, U6 small nuclear 859, pseudogene)
Gene: Small nuclear RNA gene on chromosome 21 (43,919,795 to 43,919,901, reverse strand). Ensembl gene ENSG00000199598.
Homologues: Orthologues: chimpanzee U6 (99% identical), macaque U6 (85% identical), pig U6 (61% identical). Paralogues in human: RNU6-29P (85% identical), RNU6-20P (84% identical), RNU6-10P (83% identical), RNU6-1145P (83% identical), RNU6-140P (83% identical), RNU6-25P (83% identical), RNU6-33P (83% identical), RNU6-38P (83% identical), RNU6-393P (83% identical), RNU6-41P (83% identical), RNU6-48P (83% identical), RNU6-953P (83% identical), and 1287 more.